APP (amyloid beta precursor protein)
Diseases named in the same sentence as APP in open-access papers (continued):
Sharing a sentence is not in itself a finding about the gene and the disease.
Alzheimer disease (continued). "APP has been implicated in Alzheimer's disease causation, and in addition to its importance in neurology, APP is deregulated in cancer cells." (PMID 26840089, 2016). "In fact several Alzheimer’s disease related proteins, such as APP and TAU, exhibit pathology associated hyperphosphorylated states." (PMID 27466139, 2016). "We therefore examined the effects of the overexpression of a mutant human APP mutation, linked to an early-onset form of Alzheimer’s disease, in Tg2576 mice on object recognition memory." (PMID 26868479, 2016). "One hallmark of Alzheimer ́s disease are senile plaques consisting of amyloid beta (Aβ), which derives from the processing of the amyloid precursor protein (APP)." (PMID 28005987, 2016). "Familial Alzheimer’s disease (FAD) is caused by mutations in the amyloid precursor protein (APP) or presenilin (PS)." (PMID 27572246, 2016). "A fundamental question in Alzheimer’s disease research is how abnormal APP processing causes tau hyperphosphorylation, which is a prerequisite for neurofibrillary tangle formation." (PMID 27524794, 2016). "Alzheimer's disease (AD) is caused by the toxicity of soluble β‐amyloid oligomers that arise from the cleavage of amyloid precursor protein (APP) by secretase enzymes." (PMID 26865271, 2016). "Characteristic features of Alzheimer’s disease are memory loss, plaques resulting from abnormal processing of amyloid precursor protein (APP), and presence of neurofibrillary tangles and dystrophic neurites containing hyperphosphorylated tau." (PMID 27524794, 2016). "APP mutations in the human population which increase or decrease APP processing by BACE1 can promote or protect against the development of Alzheimer’s disease, respectively." (PMID 27456313, 2016). "Amyloid precursor protein (APP), commonly associated with Alzheimer’s disease, also marks axonal degeneration." (PMID 28008944, 2016). "We uncover and exploit substrate cleavage preferences dictated by these three pockets to investigate the mechanism by which familial Alzheimer’s disease mutations within APP increase the production of pathogenic Aβ species." (PMID 27580372, 2016). "The Amyloid Precursor Protein (APP) is the source of beta-amyloid (Aβ) peptide fragments that accumulate in Alzheimer's disease (AD), but APP also has been implicated in multiple aspects of neurogenesis and neuronal differentiation." (PMID 27932950, 2016). "Amyloid beta (Aβ) is the major constituent of senile plaques in Alzheimer’s disease (AD), caused by the abnormal processing of Amyloid Precursor Protein (APP)." (PMID 27544758, 2016). "Alzheimer’s disease (AD) is thought to be caused by accumulation of amyloid-β protein (Aβ), which is a cleavage product of amyloid precursor protein (APP)." (PMID 25862638, 2015). "Beta-amyloid (Aβ), a major pathological hallmark of Alzheimer's disease (AD), is derived from amyloid precursor protein (APP) through sequential cleavage by β-secretase and γ-secretase enzymes." (PMID 25740315, 2015). "Alzheimer’s disease has been linked to mutations in a gene encoding the amyloid precursor protein (APP)." (PMID 26551565, 2015). "In familial forms of Alzheimer’s disease, mutations in Amyloid precursor protein (APP), Persenilin-1 (PSEN1), and Presenilin-2 (PSEN2) genes lead to excessive formation of neurotoxic peptide amyloid- β (Aβ) plaques which aggregate extracellularly." (PMID 25690002, 2015). "Familial Alzheimer’s disease (AD), mostly associated with early onset, is caused by mutations in three genes (APP, PSEN1, and PSEN2) involved in the production of the amyloid β peptide." (PMID 25914626, 2015). "By sequencing the whole genomes of 2,630 Icelanders, followed by imputation into large sets of GWAS data, novel associations between rare variants in APP and Alzheimer's disease and between rare variants in PDX1 and T2D were identified." (PMID 25709717, 2015).
Alzheimer disease (continued). "This binding leads to transport of the protease to the post-synaptic membrane and in an Alzheimer Disease (AD) context causes an increased α-secretase cleavage of APP." (PMID 25999813, 2015). "The age-dependent deposition of amyloid-β peptides, derived from amyloid precursor protein (APP), is a neuropathological hallmark of Alzheimer's disease (AD)." (PMID 26549211, 2015). "The A673T mutation in the amyloid precursor protein (APP) protects against Alzheimer’s disease by reducing β-amyloid protein (Aβ) production." (PMID 26531305, 2015). "The in vivo relevance of the NLRP3 inflammasome in Alzheimer's disease has recently been demonstrated in the APP/PS1 mouse model where NLRP3-deficient mice show less severe disease symptoms." (PMID 26091541, 2015). "APP, a protein which plays a central role in the pathology of Alzheimer’s disease, is part of the protein association network in both AD-iPS neuron cultures as well as in the association network built from the overlap of both experiments." (PMID 25765079, 2015). "The amyloid precursor protein (APP) has been implicated in the pathogenesis of Alzheimer’s disease (AD)." (PMID 26597721, 2015). "Amyloid-β precursor protein (APP) is a highly conserved single transmembrane protein with a receptor-like structure and has been linked with Alzheimer disease while its normal physiological function is unclear." (PMID 25491510, 2014). "BACE1 is a membrane protease which is implicated in Alzheimer's Disease by promoting cleavage of Amyloid Precursor Protein (APP) to form Amyloid-Beta 1-42 (Abeta 1-42) peptide." (PMID 24605084, 2014). "This signaling involves physiological mediators of synaptic development, maintenance, repair, and remodeling, including APP, its derivative peptides, ApoE, and tau, and is modulated by all of the many disparate factors associated with Alzheimer's disease." (PMID 25324467, 2014). "APP is a transmembrane protein, the cleavage of which generates peptides, some of which are associated with Alzheimer's disease." (PMID 25111155, 2014). "Amyloid-β precursor protein (APP) is a highly conserved single transmembrane protein that has been linked to Alzheimer disease." (PMID 25491510, 2014). "The alteration in the proteolytic cleavage of the APP-TM domain has been linked to the pathogenesis of Alzheimer disease." (PMID 24469457, 2014). "To this end, we used Tg6799 transgenic mice, which contain mutant human APP with Swedish (K670N, M671L), Florida (I716V), and London (V717I) Familial Alzheimer’s Disease (FAD) mutations, as well as human PS1 with M146L and L286V FAD mutations." (PMID 25086961, 2014). "Altered production of β-amyloid (Aβ) from the amyloid precursor protein (APP) is closely associated with Alzheimer’s disease (AD)." (PMID 25350374, 2014). "A hallmark of Alzheimer ́s disease (AD) is the deposition of Aβ peptides, produced by sequential cleavage of the amyloid precursor protein (APP) by β- and γ-secretase." (PMID 24684730, 2014). "Among those, the amyloid precursor protein (APP) and the beta amyloid peptide (Aβ) are largely associated with the development of Alzheimer’s disease (AD)." (PMID 25278878, 2014). "Deposition of β-amyloid peptides (Aβ) derived from the proteolytic processing of the amyloid precursor protein (APP) in the brain is a defining pathological hallmark of Alzheimer’s disease (AD)." (PMID 25108425, 2014). "Strikingly TKV motility and p-Mad signaling were disrupted in larvae expressing two human disease proteins; expansions of glutamine repeats (polyQ77) and human amyloid precursor protein (APP) with a familial Alzheimer's disease (AD) mutation (APPswe)." (PMID 25127478, 2014).
Alzheimer disease (continued). "An association of APP levels with Alzheimer disease (AD) has been demonstrated in several studies, with evidences showing that APP is concentrated at neuronal synapses and in AD-associated amyloid plaques following proteolysis." (PMID 24858274, 2014). "Alzheimer's disease (AD) is a complex disorder with some cases known to be caused by mutations in 3 genes: the amyloid precursor protein (APP), Presenilin 1 (PSEN1), and Presenilin 2 (PSEN2)." (PMID 24958194, 2014). "Recently, this technology was used to identify a functional variant that protects against Alzheimer’s disease in the amyloid precursor protein (APP)." (PMID 24244562, 2013). "Deletion of one copy of the kinesin light chain was reported to increase the level of APP-derived Aβ peptides in brains of mice that express APP mutants associated with Alzheimer’s disease." (PMID 24023935, 2013). "Amyloid precursor protein (APP) is the parent molecule of the neurotoxic amyloid-β, implicated in the aetiology of Alzheimer’s disease." (PMID 23742273, 2013). "Up to 5% of Alzheimer's disease (AD) is familial in origin, arising from single mutations in one of three genes, APP, PSEN1 and PSEN2." (PMID 23153828, 2013). "Recent studies have examined possible associations of miR-153 with Alzheimer's disease after functional studies confirmed an interaction with APP and amyloid beta precursor-like protein 2 (APLP2) mRNA transcripts." (PMID 24133413, 2013). "APP (most notable for its association with Alzheimer's Disease) plays multiple roles, for instance that of a neuronal growth factor and in transcriptional regulation, with complicated post-translational processing resulting in multiple cleaved peptides." (PMID 24143878, 2013). "Amyloid beta (Aβ) is considered as a pathogenic agent of Alzheimer’s disease that is processed from amyloid precursor protein (APP) by γ-secretase (GS)." (PMID 23950991, 2013). "γ-Secretase is an integral membrane protease that cleaves the amyloid precursor proteins (APP) to release Aβ peptides, which have a causative role in the pathogenesis of Alzheimer’s disease (AD)." (PMID 23994969, 2013). "The amyloid precursor protein (APP) is a type I transmembrane glycoprotein, encoded by a single gene on chromosome 21q21, which is causally involved in Alzheimer’s disease (AD)." (PMID 23874953, 2013). "The second most common monogenic form of Alzheimer's Disease involves APP mutations and duplication, accounting for 2–18% and 8% of autosomal dominant early onset cases, respectively." (PMID 24377094, 2013). "Altered proteolysis of the amyloid precursor protein (APP) is a central event in the development of pathology associated with Alzheimer's disease (AD)." (PMID 23469123, 2013). "This shift in focus is crucial for development of novel therapeutic approaches, since considerable experimental evidences indicated that changes in APP metabolism can be the common pathogenic process in different alleged causes of Alzheimer's disease." (PMID 23308095, 2013). "We have found that the Alzheimer’s disease (AD) associated amyloid-β precursor protein (APP), especially its neuroprotective processing product, secreted APP α, is elevated in persons with autism." (PMID 23801940, 2013). "We apply the method on γ-secretase, the enzyme complex that catalyzes the cleavage of the amyloid precursor protein (APP) to generate amyloid β-peptide (Aβ), the major causative agent in Alzheimer disease (AD)." (PMID 23717518, 2013). "The amyloid-β precursor protein (APP), which is better known in association with Alzheimer’s disease (AD), is a known cell adhesion and neurite pruning protein." (PMID 23801940, 2013). "Amyloid precursor protein (APP) proteolysis is fundamental for production of amyloid-β (Aβ) peptides implicated in Alzheimer’s disease (AD) pathology." (PMID 23977176, 2013). "Post-injury enzymatic cleavage of APP can generate amyloid-β (Aβ) peptides, a hallmark finding in Alzheimer’s disease (AD)." (PMID 23805125, 2013).
Alzheimer disease (continued). "APP/PS1 double-transgenic mouse models of Alzheimer's disease (AD), which overexpress mutated forms of the gene for human amyloid precursor protein (APP) and presenilin 1 (PS1), have provided robust neuropathological hallmarks of AD-like pattern at early ages." (PMID 24089686, 2013). "In a notable recent discovery, Jonsson and colleagues discovered a rare mutation (A673T) in the APP gene that was protective against Alzheimer's disease." (PMID 24278680, 2012). "For example, CX3CR1-deficient mice showed reduced inflammation and injury in models of cerebral ischemia, Alzheimer's disease (AD), and mutant tau/APP-associated neurodegeneration." (PMID 22536384, 2012). "Mutations in amyloid precursor protein (APP) have been most intensely studied in brain tissue for their link to Alzheimer’s disease (AD) pathology." (PMID 22912823, 2012). "We conclude that the clinical features of Alzheimer’s disease can be different even when caused by the same mutation in the APP gene." (PMID 22702962, 2012). "APP has been suspected as a major player in this pathology and increased copy number of APP in human is associated with Alzheimer's disease." (PMID 22848846, 2012). "The brain accumulation of a neurotoxic proteolytic derivative of the amyloid precursor protein (APP) (A-beta 40/42 peptides) is the essential event in the pathogenesis of Alzheimer's disease (AD) leading to neuronal loss." (PMID 22482075, 2012). "In a multicenter study of familial and sporadic Alzheimer's disease, Tanzi and colleagues concluded that mutations in the APP gene account for a small portion of FAD cases." (PMID 24278680, 2012). "One of the events associated with Alzheimer's disease is the dysregulation of α- versus β-cleavage of the amyloid precursor protein (APP)." (PMID 22768208, 2012). "BRI2 is an inhibitor of amyloid-β precursor protein (APP) processing, which is genetically linked to Alzheimer’s disease (AD) pathogenesis." (PMID 22537414, 2012). "Accordingly, Tip60 has been implicated in the neurodegenerative disorder Alzheimer's disease (AD) via transcriptional regulatory complex formation with the AD linked amyloid precursor protein (APP) intracellular domain (AICD)." (PMID 22848598, 2012). "Adults with DS develop early-onset Alzheimer's disease (AD), probably due to increased expression of a gene on chromosome 21 that encodes the amyloid precursor protein (APP)." (PMID 22888453, 2012). "In an analogous example, a mutation in an uORF in the mRNA encoding the BACE-1 protein (required for maturation of the Alzheimer’s Disease (AD)-associated Amyloid Precursor Protein (APP) into Amyloid β) is present in some patients with AD." (PMID 22708490, 2012). "The brain accumulation of a neurotoxic proteolytic derivative of the amyloid precursor protein (APP) is the essential event in the pathogenesis of Alzheimer's disease (AD) leading to neuronal loss." (PMID 22482075, 2012). "Alzheimer's disease (AD) is caused by accumulation of Aβ, which is produced through sequential cleavage of β-amyloid precursor protein (APP) by the β-site APP cleaving enzyme (BACE1) and γ-secretase." (PMID 21829577, 2011). "MOCA is also linked to Alzheimer's disease (AD),where it accumulates in neurofibrillary tangles and modulates beta-amyloid (APP)precursor processing." (PMID 21283588, 2011). "Alzheimer's disease susceptibility genes, APP and gamma-secretase, are involved in the herpes simplex life cycle, and that of other suspect pathogens (C. pneumoniae, H. pylori, C. neoformans, B. burgdorferri, P. gingivalis) or immune defence." (PMID 22254144, 2011). "Amyloid β (Aβ), a causative peptide of Alzheimer's disease, is generated by intracellular metabolism of amyloid β-protein precursor (APP)." (PMID 21818298, 2011). "Familial Alzheimer’s disease is associated with mutations in one of three possible genes: APP on chromosome 21, PSEN1 on chromosome 14 or PSEN2 on chromosome 1." (PMID 22654716, 2011).
Alzheimer disease (continued). "When crossed with transgenic mice with APP mutations (models of Alzheimer’s disease with amyloid plaque formation and memory deficits), p75NTR knockout mice showed a reduced degeneration in cholinergic neurites despite no reduction in Aβ levels." (PMID 22654716, 2011). "APP became the subject of intense investigation when it was identified as a risk factor for Alzheimer's disease (AD)." (PMID 21518451, 2011). "More than half of all familiar APP mutations of Alzheimer’s disease fall on its transmembtrane (TM) domain and juxtamembrane regions." (PMID 22649674, 2011). "More than half of the APP mutations found to be associated with familial forms of Alzheimer’s disease are located in its transmembrane domain." (PMID 22649674, 2011). "Since altered APP is a known risk factor for Alzheimer's disease, which has been linked to transport defects, interactions of APP with HSV1 are potentially significant." (PMID 21483850, 2011). "Promoter mutations that increase the expression of APP are associated with the development of Alzheimer disease and a duplication of the APP gene locus causes autosomal dominant early-onset Alzheimer disease." (PMID 20205906, 2010). "In DS, triplication of chromosome 21 invariably includes the APP gene (21q21) encoding the Alzheimer's disease (AD) amyloid precursor protein (APP)." (PMID 20502642, 2010). "Although many authors have implicated the lysosome in the pathophysiology of Alzheimer's disease, lysosomes are typically viewed as downstream sites in the trafficking of APP and the production and clearance Aβ." (PMID 20409323, 2010). "Previous studies using transgenic mouse modes of Alzheimer's disease have resulted in little consensus on the effects of mutations in APP and PS1 with respect to LTP." (PMID 20630068, 2010). "Endoproteolytic cleavage of APP yields the pathogenic amyloid-β peptides (Aβ) that progressively accumulate in the brain as the diffuse and neuritic plaques of Alzheimer's disease (AD)." (PMID 20502642, 2010). "X11s associate with the cytoplasmic domain of amyloid β-protein precursor (APP) and suppress APP metabolism, including amyloid β-protein (Aβ) generation, which is widely believed to be the major cause of Alzheimer's disease (AD) pathogenesis." (PMID 20843325, 2010). "Transgenic mice expressing mutated amyloid precursor protein (APP) and presenilin (PS)-1 or -2 have been successfully used to model cerebral β-amyloidosis, one of the characteristic hallmarks of Alzheimer's disease (AD) pathology." (PMID 19936202, 2009). "Until now, functional analyses of this complex are available only in Embryophyta and Metazoa, where it is known to be involved in the cleavage of Notch and other proteins such as ErbB4 and APP (amyloid precursor protein, implicated in Alzheimers disease)." (PMID 19825158, 2009). "Mutations of the amyloid precursor protein gene (APP) are found in familial forms of Alzheimer's disease (AD) and some lead to the elevated production of amyloid-β-protein (Aβ)." (PMID 19997607, 2009). "These are all APP mutations that in humans cause familial forms of Alzheimer's disease, except for APP-Ncas that is an APP construct missing the COOH-terminal 31 amino acids." (PMID 19849849, 2009). "As impaired insulin signalling (IIS) is a risk factor for Alzheimer’s disease we crossed mice (Tg2576) over-expressing human amyloid precursor protein (APP), with insulin receptor substrate 2 null (Irs2−/−) mice which develop insulin resistance." (PMID 19523444, 2009). "The most common animal models currently used for Alzheimer disease (AD) research are transgenic mice that express a mutant form of human Aβ precursor protein (APP) and/or some of the enzymes implicated in their metabolic processing." (PMID 19355852, 2009).